TCOF1 (treacle ribosome biogenesis factor 1)
Diseases named in the same sentence as TCOF1 in open-access papers (continued):
Sharing a sentence is not in itself a finding about the gene and the disease.
Intellectual disability (2 papers, 2020 to 2024). "The novel TCOF1 c.1371_1372insT mutation was associated with mild craniofacial manifestations and very rare symptoms of TCS, i.e., developmental delay and moderate intellectual disability." (PMID 39518953, 2024).
Lissencephaly (2 papers, 2015 to 2025). A spectrum of malformations of cortical development caused by insufficient neuronal migration that subsumes the terms agyria, pachygyria and subcortical band heterotopia. "Cortical disruptions that derive from mutations in genes such as NDE1, LIS1, PP4c, WDR62, CENPE, TCOF1, AGS3, VANGL2 and HTT, are classified as micro- or macro-cephaly, and/or cortical disorganization and abnormal cortical architecture, lissencephaly and simplified gyral patterns." (PMID 25729350, 2015).
microtia (2 papers, 2024). "As reported in this review, the major gene disorder related to microtia phenotype is found in TCOF1 (32.82%; 28 cases), followed by GSC exon 2 (6.82%), FANCB (4.55%), SIX2 (3.41%), HSPA9 (3.41%) and CDT1 (3.41%) with each characteristic." (PMID 38594752, 2024). "In the syndromic microtia group, the most common genes were TCOF1 (43.75%; 28 out of 64 cases), SIX2 (4.69%), and HSPA9 in (4.69%) patients." (PMID 38594752, 2024). "We also found in our review that the TCOF1 gene was most commonly found in microtia patients with TCS." (PMID 38594752, 2024). "Nevertheless, TCOF1 and HOXA2, in turn, cause microtia in a dominant manner, suggesting haploinsufficiency, while HSPA9 and GSC are in recessive mode of inheritance." (PMID 38594752, 2024). "We found 88 cases of genetic data related to microtia, including TCOF1 (31.82%), GSC exon 2 (6.82%), FANCB (4.55%), SIX2 (3.41%), HSPA9 (3.41%), and CDT1 (3.41%)." (PMID 38594752, 2024). "In the syndromic microtia group, the most common genes were TCOF1 (43.75%), SIX2 (4.69%), and HSPA9 (4.69%), while in the non-syndromic microtia group, the most frequently found gene was GSC exon 2 (25%), FANCB (16.67%), HOXA2 (8.33%), GSC exon 3 (8.33%), MARS1 (8.33%), and CDT1 (8.33%)." (PMID 38594752, 2024). "In addition, HSPA9, MARS1, and TCOF1 were the only genes related to familial microtia." (PMID 38594752, 2024). "This study showed different results from a previous study that found three genes most related to the development of microtia HOXA2, followed by FGF3 and TCOF1, the third most common genes." (PMID 38594752, 2024). "Based on our findings, 64 cases (72.72%) were syndromic microtia [TCOF1 (43.75%), SIX2 (4.69%), and HSPA9 (4.69%)] and 24 cases (27.27%) were non-syndromic microtia [GSC exon 2 (25%), FANCB (16.67%), HOXA2 (8.33%), GSC exon 3 (8.33%), MARS1 (8.33%), CDT1 (8.33%)]." (PMID 38594752, 2024).
osteosarcoma (2 papers, 2021 to 2022). A usually aggressive malignant bone-forming mesenchymal neoplasm, predominantly affecting adolescents and young adults. "Furthermore, overexpression of TCOF1 has been associated with radioresistance in acinar progenitor cells of rat salivary glands, but attenuated TCOF1 expression can sensitize human osteosarcoma cells to irradiation." (PMID 35093935, 2022). "Similarly, silencing of TCOF1 in human osteosarcoma cells sensitized the cells to irradiation and cisplatin treatment." (PMID 33804586, 2021).
3M syndrome (1 paper, 2025). 3M syndrome is a primordial growth disorder characterized by low birth weight, reduced birth length, severe postnatal growth restriction, a spectrum of minor anomalies (including facial dysmorphism) and normal intelligence. "We found SMU1 to be associated with 3M syndrome, and TCOF1 to be associated with BBSome complex responsible for Bardet Biedl syndrome." (PMID 41312386, 2025).
Brachycephaly (1 paper, 2025). An abnormality of skull shape characterized by a decreased anterior-posterior diameter. "In contrast, Tcof1+/– embryos of the DBA/1J/C57BL/6 background exhibit brachycephaly and microphthalmia and largely phenocopy the severe clinical features of TCS in humans." (PMID 40699891, 2025).
breast tumours (1 paper, 2022). "Another potential reason for the combinatorial effects is that basal-like breast tumours are enriched in genes regulating cell proliferation, which could result in the enhancement of antitumour effects by chemotherapeutic agents upon TCOF1 knockout." (PMID 34718356, 2022).
cleft palate (1 paper, 2021). Cleft palate is a fissure type embryopathy that affects the soft and hard palate to varying degrees. "It remains to be determined whether TCOF1, BRCA1, and BRCA2 genetically interact in palate development, and for this reason it is important to study how these specific DDR-related elements are involved in the etiology of cleft palate." (PMID 33854442, 2021).
conductive hearing loss (1 paper, 2024). "Both male probands suffered from severe craniofacial malformations, and one of them had conductive hearing loss, whereas the mothers of the probands carrying the same mutation in the TCOF1 gene were completely unaffected." (PMID 39518953, 2024).
Cornelia de Lange syndrome (1 paper, 2024). A rare syndrome characterized by low birth weight, delayed growth, intellectual disabillity, behavioral problems, and a distinctive facial appearance (thin, arched eyebrows, low set ears, small teeth, and small nose). "Estimations of Sanger sequencing prices were performed for five genes most commonly associated with RASopathies (BRAF, NF1, PTPN11, RAF1, and SOS1), and three genes, TCOF1, CHD7, and NIBPL most commonly associated with Treacher Collins, CHARGE, and Cornelia de Lange syndromes, respectively." (PMID 37815686, 2024).
diffuse large B-cell lymphoma (1 paper, 2022). "Expression of TCOF1 was upregulated in diffuse large B-cell lymphoma (DLBCL), sarcoma (SARC), testicular germ cell tumor (TGCT), and thymoma (THYM)." (PMID 35093935, 2022).
epilepsy (1 paper, 2022). A brain disorder characterized by episodes of abnormally increased neuronal discharge resulting in transient episodes of sensory or motor neurological dysfunction, or psychic dysfunction. "As FHFs and NOLC1/TCOF1 are implicated in severe disease, including epilepsy, cancer and ribosomopathy, future studies should aim to decipher the functional interplay between FHF proteins and NOLC1/TCOF1." (PMID 36411431, 2022).
first arch branchial syndrome (1 paper, 2024). "A variant in the TCOF1 gene will disrupt neural crest cell migration into the first arch during the fourth week of pregnancy, which can be called the first arch branchial syndrome." (PMID 38594752, 2024).
glioblastoma (1 paper, 2022). The most malignant astrocytic tumor (WHO grade IV). "Lower expression of TCOF1 in tumor was found only in glioblastoma multiforme (GBM)." (PMID 35093935, 2022).
glioma (1 paper, 2022). A benign or malignant brain and spinal cord tumor that arises from glial cells (astrocytes, oligodendrocytes, ependymal cells). "Survival analysis results then indicated that TCOF1 was correlated with prognosis in several cancers, including BC, UVM, liposarcoma, RCC, glioma, meningioma, and CRC." (PMID 35093935, 2022). "Of these, high expression levels of TCOF1 were detrimental to patient prognosis in BC, UVM, liposarcoma, glioma, and meningioma, but they played a protective role in RCC and CC." (PMID 35093935, 2022).
intestinal motility disorders (1 paper, 2024). "They found that mice with the presence of complex Pax3/Tcof1 exhibited a severe reduction in neural crest cell population and migration of neural crest cells to the colon, resulting in intestinal motility disorders in mice." (PMID 38444283, 2024).
lung carcinoma (1 paper, 2022). "However, in certain studies, TCOF1 was less expressed in brain, central nervous system (CNS), head and neck, kidney, and lung cancers and in lymphoma." (PMID 35093935, 2022).
lymphoma (1 paper, 2022). A malignant (clonal) proliferation of B- lymphocytes or T- lymphocytes which involves the lymph nodes, bone marrow and/or extranodal sites. "The results showed that TCOF1 expression in tumors was significantly higher than in normal tissues in many cancers, including bladder, breast, cervical, colorectal, esophageal, gastric, head and neck, liver, lung, and ovarian, as well as in melanoma and lymphoma." (PMID 35093935, 2022).
mesothelioma (1 paper, 2022). A usually malignant and aggressive neoplasm of the mesothelium which is often associated with exposure to asbestos. "High expression levels of TCOF1 were related to poor prognosis for overall survival (OS) in kidney chromophobe (KICH; P = 0.014), PRCC (P = 0.0027), LIHC (P = 0.0037), and mesothelioma (MESO, P = 0.0091) in TCGA datasets." (PMID 35093935, 2022).
microcephaly (1 paper, 2012). A congenital or acquired developmental disorder in which the circumference of the head is smaller than normal for the person's age and sex. "Similar to our Tcof1/Treacle loss-of-function studies, mitotically-arrested cells are considerably increased in association with altered spindle orientation in the VZ of Nde1 mutant mice which exhibit defects in cortical neurogenesis and microcephaly." (PMID 22479190, 2012). "TCS is caused by mutations in the TCOF1 gene, which encodes a nucleolar phosphoprotein known as Treacle however, a role for TCOF1/Treacle in cortical neurogenesis and the regulation of brain size and pathogenesis of microcephaly has not been previously examined." (PMID 22479190, 2012).
neuroblastoma (1 paper, 2023). Neuroblastoma (NB) is the most common solid, extracranial childhood tumor. "Deletion of Tcof1 in murine neuroblastoma cell line changed the expression pattern of genes associated with various processes, such as cell cycle and development, beyond ribosomal DNA regulation." (PMID 37378024, 2023).
skin cancer (1 paper, 2022). "IHC staining results showed that high expression of TCOF1 could be observed in colorectal (36.4%), testicular (16.67%), pancreatic (11.11%), urothelial (10%), stomach (9.09%), liver (8.33%), endometrial (8.33), ovarian (8.33%), renal (8.33%), and skin cancers (8.33%)." (PMID 35093935, 2022).
skin cutaneous melanoma (1 paper, 2022). "Notably, TCOF1 expression in skin cutaneous melanoma (SKCM) metastatic tissue was remarkably higher than in respective primary tumor tissue." (PMID 35093935, 2022).
tumor (9 papers, 2015 to 2026). "First, our research revealed that TCOF1 deficiency significantly inhibits tumor cell migration, suggesting TCOF1 plays a crucial role in cellular motility." (PMID 42193052, 2026). "For instance, the TCOF1 and Lis1 are found to be associated with cancer-associated proteins, functioning as either oncogenes or tumor suppressors." (PMID 41312386, 2025). "We present novel evidence that in these irradiated tumor cells, Treacle ribosome biogenesis factor 1 (TCOF1), a nucleolar protein that is important in ribosome biogenesis, facilitates nucleolar translocation of GLI1." (PMID 37380890, 2023). "To further understand the mechanism of TCOF1 in tumor pathogenesis, we investigated genes and proteins related to TCOF1 expression and conducted pathway enrichment analyses thereof." (PMID 35093935, 2022). "Furthermore, we present evidence that in these irradiated tumor cells, Treacle ribosome biogenesis factor 1 (TCOF1), a nucleolar protein that is important in ribosome biogenesis, facilitates nucleolar translocation of GLI1." (PMID 37380890, 2023). "Depletion of TCOF1 in basal-like MDA-MB-468 cells resulted in a profound decrease of tumour growth." (PMID 34718356, 2022). "Finally, potential pathways involving TCOF1 in tumor pathogenesis were also investigated." (PMID 35093935, 2022). "To gain a better understanding and to expand upon this observation, we irradiated tumor cells and stained for GLI1, POLR1A, and TCOF1." (PMID 37380890, 2023). "Taken together, these data demonstrate an important function of TCOF1 in regulating CSC self-renewal and tumour initiation." (PMID 34718356, 2022). "Since our data of clonogenic assay suggest that TCOF1 regulates progeny producing capability, we next investigated if TCOF1 regulates CSC properties and tumour-initiating ability." (PMID 34718356, 2022). "Among them, three genes (RAB10, TCOF1, and PSMD14) were found to be significantly upregulated in tumor samples, and univariate Cox regression showed that they were also significantly associated with overall survival." (PMID 36171884, 2022). "In irradiated tumor cells, the hedgehog pathway transcription factor GLI1 becomes activated and translocates to the nucleolus through the treacle ribosome biogenesis factor 1 (TCOF1)." (PMID 38633862, 2024). "Interestingly, impairment of cell proliferation in 2D and 3D by TCOF1 knockout could not be rescued by KIT overexpression, indicating that another downstream effector is responsible for mediating TCOF1’s function in cell proliferation and/or survival of bulk tumour cells." (PMID 34718356, 2022).
cancer (8 papers, 2016 to 2025). A tumor composed of atypical neoplastic, often pleomorphic cells that invade other tissues. "We further investigated the association between TCOF1 expression and cancer patients’ prognoses in TCGA databases via GEPIA2." (PMID 35093935, 2022). "Analysis of transcriptomic data from >500 uterine carcinoma patients demonstrates that TCOF1 alterations can be detected in nearly 10% of the analyzed cancer samples, with a clear hot spot mutation affecting codon 298 and the resulting substitution of leucine with isoleucine or phenylalanine." (PMID 33804586, 2021). "In this work, we visualized the expression and prognostic landscapes of TCOF1 in pan-cancer based on published data." (PMID 35093935, 2022). "In the context of cancer, our bioinformatics analysis on public data sets uncovered a super-enhancer that potentially drives TCOF1 expression." (PMID 34718356, 2022). "Based on the CPTAC dataset, we then evaluated protein expression of TCOF1 in pan-cancer via the UALCAN portal." (PMID 35093935, 2022). "Since tumorigenesis is a complex process involving multiple pathways, our study provided only preliminary findings on the oncogenic role of TCOF1; its exact role in certain type of cancers should be evaluated and validated more precisely and comprehensively." (PMID 35093935, 2022). "According to the results of expression analysis, TCOF1 was upregulated in most cancer types when compared to corresponding normal tissues." (PMID 35093935, 2022). "To understand how TCOF1 affects the prognoses of cancer patients, we analyzed the relationship between survival outcomes and TCOF1 expression levels via PrognoScan." (PMID 35093935, 2022). "Expression of TCOF1 and its correlations with other variables in cancers on the chromosomal level (including DNA methylation, somatic copy number, microRNA expression, somatic mutation, and protein level) is displayed in Circos plots." (PMID 35093935, 2022). "In this work, we used integrated bioinformatics methods to comprehensively analyze the role of TCOF1 and its corresponding protein treacle in different types of cancers." (PMID 35093935, 2022). "Given that TCOF1 participates in several key cellular processes, in this study we aimed to investigate the part it plays in human cancers." (PMID 35093935, 2022). "To further evaluate differential expression of TCOF1 in pan-cancer, we compared RNA sequencing data from TCGA using TIMER." (PMID 35093935, 2022). "We observed a significant and positive correlation between TCOF1 and DNMTs in almost all types of cancer except UCS and CHOL." (PMID 35093935, 2022). "We examined TCOF1 mRNA expression levels in various cancer types by analyzing TCGA data via Oncomine." (PMID 35093935, 2022). "The significance of these mutations remains to be clarified; however, studies in cell lines derived from other tumor types suggest that TCOF1 disruption can affect functioning of cancer cells." (PMID 33804586, 2021). "Yet, the disease-associated overexpression and function of TCOF1 in human cancers have never been characterised." (PMID 34718356, 2022). "With the emergence of large-scale, multi-omics, and publicly accessible databases containing sample data from different types of cancer, it is now possible to analyze and evaluate the role of certain genes of interest, namely TCOF1 in this study, at the pan-cancer level." (PMID 35093935, 2022). "We also investigated TCOF1 protein expression in 20 types of cancer using the HPA cohort." (PMID 35093935, 2022). "As there is no report on the role of TCOF1 in cancer, nor any association of TCOF1 overexpression with any disease, here we focussed on the SE324–TCOF1 pair and determined the functional importance of TCOF1 in breast tumorigenesis." (PMID 34718356, 2022). "TCOF1 was upregulated in most types of cancers, and we believe it might serve as a prognostic biomarker depending on cancer type." (PMID 35093935, 2022). "In summary, we presented a broad view of TCOF1’s role in pan-cancer." (PMID 35093935, 2022).
cancer (continued). "Our findings indicated that TCOF1 might exert an essential effect on cancer development and it might serve as a potential therapy target." (PMID 35093935, 2022). "Importantly, TCOF1 is minimally expressed in normal breast tissues adjacent to TNBC (Cancer RNA-seq Nexus database." (PMID 34718356, 2022). "This indicated that upregulated expression of TCOF1 in different cancers might contribute to DNA methylation." (PMID 35093935, 2022). "Surprisingly, the studies directly analyzing the role of TCOF1 in cancer are limited." (PMID 33804586, 2021). "The promising results of studies indicating that TCOF1 silencing sensitizes cancer cells to radiotherapy and cisplatin treatment suggest that drugs targeting treacle could be possibly used in combination therapies." (PMID 33804586, 2021). "All these data, although limited, suggest that TCOF1 dysfunction may possibly contribute to cancer development and progression." (PMID 33804586, 2021). "Notably, in 20 of 33 types of cancer, CD276 expression was remarkably associated with TCOF1." (PMID 35093935, 2022). "TCOF1 plays a critical role in craniofacial development but its function in cancer remains unclear." (PMID 34718356, 2022). "Although they did not verify this hypothesis experimentally, they noted that TCOF1 deficiency could prevent or delay cancer development, consistently with the lack of data on cancer cases among TCS patients." (PMID 33804586, 2021). "Additionally, TCOF1 expression level was significantly associated with infiltration levels of Cluster of Differentiation 8–positive (CD8+) T cells, CD4+ T cells, B cells, neutrophils, macrophages, and dendritic cells (DCs) in 14, 16, 12, 20, 13, and 17 cancer types, respectively." (PMID 35093935, 2022). "The result of qRT-PCR revealed that PDCD6, TCOF1 and FAM83D were highly expressed in HCC cancer cells." (PMID 33712026, 2021). "Although the function of TCOF1 is rarely reported in carcinoma, its expression level is high in HCC tissues and HCC cell lines according to our finding, which may provide foundation for the further investigation of the association between TCOF1 and tumorigenesis." (PMID 33712026, 2021). "We analyzed the correlation between TCOF1 expression and TMB across various cancer types." (PMID 35093935, 2022). "Finally, hematopoietic stem cells (HSCs), had a negative relationship with TCOF1 expression in most types of cancer." (PMID 35093935, 2022). "In line with the molecular functions of the selected genes modulating transcription (BPTF, DDX21), protein translation (NOLC1, TCOF1), or nuclear import (KPNA2) it is feasible to speculate that restoring their cellular content in cancer cells could facilitate viral production." (PMID 34203557, 2021).